RING1 (ring finger protein 1)
Description:
Constitutes one of the E3 ubiquitin-protein ligases that mediate monoubiquitination of 'Lys-119' of histone H2A, thereby playing a central role in histone code and gene regulation. H2A 'Lys-119' ubiquitination gives a specific tag for epigenetic transcriptional repression and participates in X chromosome inactivation of female mammals. Essential component of a Polycomb group (PcG) multiprotein PRC1-like complex, a complex class required to maintain the transcriptionally repressive state of many genes, including Hox genes, throughout development. PcG PRC1 complex acts via chromatin remodeling and modification of histones, rendering chromatin heritably changed in its expressibility. Compared to RNF2/RING2, it does not have the main E3 ubiquitin ligase activity on histone H2A, and it may rather act as a modulator of RNF2/RING2 activity.
Synonyms: RING1A; RNF1
Tractability: PROTAC: ubiquitination databases record sites on it; its protein half-life has been measured.
Gene: Protein-coding gene on chromosome 6 (33,208,491 to 33,212,722, forward strand). Ensembl gene ENSG00000204227.
Subcellular location: Nucleus; Nucleus speckle
Subcellular location (Human Protein Atlas): Nucleoplasm; Cytosol
Pathways (Reactome):
Metabolism of proteins: SUMOylation of DNA damage response and repair proteins; SUMOylation of DNA methylation proteins; SUMOylation of RNA binding proteins; SUMOylation of chromatin organization proteins; SUMOylation of transcription cofactors
Gene expression (Transcription): RUNX1 interacts with co-factors whose precise effect on RUNX1 targets is not known; Transcriptional Regulation by E2F6
Cellular responses to stimuli: Oxidative Stress Induced Senescence
Developmental Biology: Differentiation of naive CD4+ T cells to T helper 2 cells (Th2 cells)
Signal Transduction: Regulation of PTEN gene transcription
Gene Ontology:
Molecular function: protein binding; chromatin binding; ubiquitin protein ligase activity; ubiquitin-protein transferase activator activity
Biological process: chromatin remodeling; negative regulation of DNA-templated transcription; heterochromatin formation; positive regulation of DNA-templated transcription; chromatin organization; protein ubiquitination
Cellular component: nucleus; PcG protein complex; PRC1 complex; chromatin; nucleoplasm; ubiquitin ligase complex; nuclear body; nuclear speck; sex chromatin
Genetic constraint (gnomAD): Loss-of-function variants: 8 observed, 34.94 expected, observed/expected ratio (o/e) 0.23, 90% interval 0.13 to 0.41. The upper end of that interval is the gene's LOEUF score, 0.41, which puts it in group 1 of 6, group 1 being the genes least tolerant of losing a copy. Missense variants: 341 observed, 530.26 expected, observed/expected ratio (o/e) 0.64, 90% interval 0.59 to 0.7. Synonymous variants: 213 observed, 221.32 expected, observed/expected ratio (o/e) 0.96, 90% interval 0.86 to 1.08.
Homologues: Orthologues: chimpanzee RING1 (99% identical), macaque RING1 (99% identical), pig RING1 (99% identical), dog RING1 (99% identical), guinea pig RING1 (98% identical), mouse Ring1 (97% identical), rat Ring1 (92% identical), tropical clawed frog ring1 (64% identical), Drosophila melanogaster Psc (31% identical), Drosophila melanogaster Su(z)2 (10% identical). Paralogues in human: RNF2 (53% identical), BMI1 (15% identical), PCGF2 (15% identical), PCGF6 (14% identical), PCGF1 (13% identical), PCGF5 (13% identical), PCGF3 (13% identical).
Diseases named in the same sentence as RING1 in open-access papers:
RING1 is named in the same sentence as 57 diseases in open-access papers, as found by Europe PMC text mining. Sharing a sentence is not in itself a finding about the gene and the disease. The quoted sentences say what the papers report.
breast cancer (4 papers, 2018 to 2024). A primary or metastatic malignant neoplasm involving the breast. "In this study, we found that RING1 is downregulated in breast cancer and that its low level of expression is associated with better OS, RFS and DMFS." (PMID 33634028, 2020). "Consistent with previous research results, we found that RING1 low protein expression was associated with poor overall survival in breast cancer patients." (PMID 33634028, 2020). "In summary, our study found that RING1 expression was downregulated in breast cancer, and its low expression was associated with worse disease outcomes." (PMID 33634028, 2020). "RING1 expression was downregulated in breast cancer, and its low expression was associated with worse disease outcomes." (PMID 33634028, 2020). "Overall, the obtained results indicate that RING1 is associated with breast cancer tumorigenesis and that it can be used as a prognostic biomarker for breast cancer." (PMID 33634028, 2020). "RING1 low expression is an unfavorable prognostic factor in many cancer patients, especially in breast cancer patients." (PMID 33634028, 2020). "We further investigated the relationship between RING1 expression and breast cancer clinicopathological features." (PMID 33634028, 2020). "Univariate and multivariate analyses were performed to explore the potential clinical significance of RING1 expression in breast cancer." (PMID 33634028, 2020). "RING1 protein expression in breast cancer and normal tissue was investigated using IHC on a tissue microarray (TMA), containing 237 human breast cancer specimens and 24 normal tissues." (PMID 33634028, 2020). "Breast cancer patients with an increased RING1 mRNA level had better OS, RFS, and DMFS than those with a low expression level." (PMID 33634028, 2020). "The results showed a significantly lower RING1 expression in breast cancer compared to that in normal tissues (P = 0.0003)." (PMID 33634028, 2020). "A low RING1 expression level was found in 164 out of 237 (69.2%) breast cancer specimens; however, this level of expression was only found in a small proportion (20.83%) of normal tissues." (PMID 33634028, 2020). "Considering that invasive ductal carcinoma (IDC) and invasive lobular carcinoma (ILC) are the two most common pathological types of breast cancer, we first analyzed RING1 expression level in breast cancer, based on histological subtypes." (PMID 33634028, 2020). "Taken together, these results suggest that RING1 may play a crucial biological function in breast cancer tumorigenesis." (PMID 33634028, 2020). "The protein expression level of RING1 in breast cancer compared to normal tissues." (PMID 33634028, 2020). "However, further research is required in determining RING1 expression and prognostic value in breast cancer." (PMID 33634028, 2020). "Next, we then focused our study on the role of RING1 in breast cancer." (PMID 33634028, 2020). "Moreover, the multivariate Cox regression model indicated that RING1 (P = 0.038) and ER (P = 0.029) expressions were independent prognostic markers for breast cancer." (PMID 33634028, 2020). "To validate this hypothesis, we investigated whether the DNA methylation level of the RING1 promoter was upregulated in breast cancer tissues compared to normal tissues." (PMID 33634028, 2020). "Due to the limited number of studies, the role of RING1 in breast cancer is unclear." (PMID 33634028, 2020).
breast cancer (continued). "However, recently published studies on RING1 role in cancer are preliminary, and additional in vivo and in vitro studies are needed to clarify the function of RING1, especially in breast cancer." (PMID 33634028, 2020). "Importantly, we have provided new evidence that RING1 is a useful biomarker and a prognostic predictor in breast cancer." (PMID 33634028, 2020). "Moreover, we found that the low RING1 expression predicts poor survival in breast cancer." (PMID 33634028, 2020). "RING1 may act as a new prognostic biomarker for breast cancer." (PMID 33634028, 2020). "Compared to RING1 which is not amplified, RNF2 amplification correlated to its significant overexpression in breast cancer compared to normal breast tissues, regardless of breast cancer subtype." (PMID 30139998, 2018).
cervical cancer (3 papers, 2018 to 2021). A primary or metastatic malignant neoplasm involving the cervix. "The lncRNA C5orf66-AS1 promoted cell proliferation in cervical cancer by targeting the miR-637/RING1 axis." (PMID 33230459, 2020). "LncRNA C5orf66-AS1, as a competitive endogenous RNA (ceRNA), regulated the effect of RING1 on the proliferation, apoptosis and cell cycle of cervical cancer cells through adsorbing miR-637." (PMID 30518760, 2018). "In summary, C5orf66-AS1 was believed to adsorb miR-637 through a ceRNA mechanism and upregulate RING1, ultimately promoting the proliferation of cervical cancer cells." (PMID 30518760, 2018). "Collectively, lncRNA C5orf66-AS1, as a ceRNA, regulated the effect of RING1 on the proliferation, apoptosis and cell cycle of cervical cancer through adsorbing miR-637." (PMID 30518760, 2018). "Exogenous miR-637 and RING1 interventions could reverse the proliferation ability mediated by C5orf66-AS1 in cervical cancer cells." (PMID 30518760, 2018).
hepatocellular carcinoma (3 papers, 2019 to 2020). A malignant tumor that arises from hepatocytes. "Interestingly, RING1 expression has been found to be upregulated in hepatocellular carcinoma tissues compared to adjacent normal tissues from cancer patients, and higher RING1 expression has been associated with poorer prognoses." (PMID 31905981, 2019). "These pieces of evidence highlighted the importance of RING1 in malignant transformation and hepatocellular carcinoma development." (PMID 33634028, 2020). "For miR-637, many studies suggest it act as a protective factor to suppress the cancer cells proliferation, invasion and migration by targeting on regulating the expression of AKt1, RING1 or NUPRI in hepatocellular carcinoma, colorectal cancer, glioma, and cervical cancer." (PMID 32788609, 2020). "At present, most of the research about RING1 focuses on liver cancer and RING1 overexpression was also observed in hepatocellular carcinoma (HCC) specimens." (PMID 33634028, 2020).
gastric cancer (2 papers, 2021). A primary or metastatic malignant neoplasm involving the stomach. "It was shown that helicobacter pylori infection elevated SNHG17 expression in gastric cancers, resulting in increased genome instability via a SNHG17/miR-3909/RING1/Rad51 pathway." (PMID 34671012, 2021). "Hp upregulated the expression of RING1/RAD51 by upregulating lncRNA SNHG17 as a ceRNA for miR-3909, changed the DNA repair system, and promoted the occurrence of gastric cancer." (PMID 34568091, 2021).
melanoma (2 papers, 2017 to 2020). A malignant, usually aggressive tumor composed of atypical, neoplastic melanocytes. "In conclusion, the study identified novel interactions between CD147 and RING1, recovered CD147 nuclear envelope distribution in melanoma cells, and suggested a new mechanism underlying how cytoplasmic CD147 promotes melanoma development." (PMID 28832687, 2017). "RING1 can bind DNA and act as a transcriptional repressor, play an important role in the aggressive phenotype in melanoma." (PMID 28832687, 2017). "In conclusion, our study identified novel interactions between CD147 and RING1, recovered CD147 nuclear envelope distribution in melanoma cells, and suggested a new mechanism underlying how cytoplasmic CD147 promotes melanoma development." (PMID 28832687, 2017). "RING1 inhibits CD147’s capability promoting melanoma cell migration." (PMID 28832687, 2017). "Similarly, ring finger protein-1 (RING1) was also found as a differently expressed gene, which is involved in epigenetic regulation in cancer, where it acts as a transcriptional repressor and plays an important role in the development of aggressive phenotypes in melanoma." (PMID 32613561, 2020).
neurodevelopmental disabilities (2 papers, 2022 to 2024). "For instance, DNV in the RING1 gene was identified in a 13-year-old girl with neurodevelopmental disabilities." (PMID 38486307, 2024). "A recent study has shown that RING1 p.R95Q, which alters a conserved arginine residue in the catalytic RING domain, results in syndromic neurodevelopmental disabilities of a 13-year-old girl." (PMID 36117635, 2022).
autoimmune disease (1 paper, 2024). A disorder resulting from loss of function or tissue destruction of an organ or multiple organs, arising from humoral or cellular immune responses of the individual to their own tissue constituents. "Dysfunction of RING1 may relate to the pathogenesis of autoimmune diseases, cancers, neurodegenerative diseases, and viral infections." (PMID 39200825, 2024).
bile duct cancer (1 paper, 2020). "The result also showed that RING1 expression was upregulated in several types of cancers, including CHOL (Bile Duct Cancer), ESCA (Esophageal Cancer), LIHC (Liver Cancer), and PCPG (Pheochromocytoma & Paraganglioma) and when compared to their non-cancer counterpart tissues." (PMID 33634028, 2020).
bladder cancer (1 paper, 2020). "For bladder cancer, a study detected RING1 expression in 85 of 93 samples, but the median relative expression was 19.98 (range 0–91.36)." (PMID 33634028, 2020). "Therefore, we speculated that RING1 is expressed at a relatively low level in bladder cancer, which requires further studies to prove." (PMID 33634028, 2020).
breast tumors (1 paper, 2020). "Taken together, these results show that RING1 is expressed a low level in breast tumors and may serve as an unfavorable prognostic maker." (PMID 33634028, 2020).
Cognitive impairment (1 paper, 2022). Abnormal cognition is characterized by deficits in thinking, reasoning, or remembering. "Patients with RING1 mutation have neurological psychosis, developmental abnormalities and cognitive impairment." (PMID 36117635, 2022). "Patients with RING1 dysfunction show neurogenic psychosis, developmental abnormalities, and cognitive impairment, suggesting that it has an important function in neural development." (PMID 36117635, 2022).
Colon Cancer (1 paper, 2020). "RING1 expression was significantly elevated in some cancers, such as liver cancer, whereas its expression was decreased in other solid cancers, such as Colon Cancer." (PMID 33634028, 2020). "Besides, we noticed that RING1 expression level was decreased in COAD (Colon Cancer), KICH (Kidney Chromophobe), KIRP (kidney papillary cell carcinoma), and THCA (Thyroid Cancer) when compared to the corresponding normal tissues." (PMID 33634028, 2020).
esophageal squamous cell carcinoma (1 paper, 2020). Esophageal squamous cell carcinoma (ESCC) is a type of esophageal carcinoma (EC) that can affect any part of the esophagus, but is usually located in the upper or middle third. "We found that RING1 low mRNA expression is related to worse OS in ESCC (esophageal squamous cell carcinoma), KIRP (kidney papillary cell carcinoma), LUAD (lung adenocarcinoma), OV (ovarian cancer), PDAD (pancreatic ductal adenocarcinoma), and THYM (thymoma)." (PMID 33634028, 2020).
Hodgkins lymphoma (1 paper, 2020). A heterogeneous group of malignant lymphoid neoplasms of B-cell origin characterized histologically by the presence of Hodgkin and Reed-Sternberg (HRS) cells in the vast majority of cases. "Although an anomalously low expression of RING1 was observed in a few proportions of Hodgkin and Reed-Sternberg (HSR) cells, most of Hodgkin’s lymphoma (HS) cases expressed a high level." (PMID 33634028, 2020).
leukemia (1 paper, 2022). A malignant (clonal) hematologic disorder, involving hematopoietic stem cells and characterized by the presence of primitive or atypical myeloid or lymphoid cells in the bone marrow and the blood. "The RNF217 protein is a member of RING1-IBR-RING24 (RBR) ubiquitin protein ligase family, which contains a transmembrane domain and regulates apoptosis signaling by interacting with HAX1 to promote leukemia development." (PMID 35654793, 2022).
liver cancer (1 paper, 2020). An epithelial or non-epithelial malignant neoplasm that arises from the liver. "Recent studies have showed that RING1 is overexpressed in various types of human cancers, including lymphoma, non-small cell lung cancer, and prostate and liver cancers." (PMID 33634028, 2020).
liver fibrosis (1 paper, 2022). "In addition, we found that other CHB-related loci, such as HSD17b8, ITPR3, NUP205, RING1, and SKIV2l, were upregulated or downregulated in different ways in the groups with different degrees of liver fibrosis." (PMID 36406135, 2022).
lung carcinoma (1 paper, 2025). "However, it could be hypothesized that, like other factors, such as genetic mutations that change normal cells into cancerous cells, there may be a trigger for RING1 downregulation to cause lung cancer." (PMID 41362702, 2025). "It was also found that RING1 KD promotes lung cancer cell proliferation by upregulating CIP2A expression followed by increase of c‐MYC, and Cyclin B1." (PMID 41362702, 2025). "CIP2A expression was regulated by RING1 and its activity affected the oncogenic capacity of lung cancer cells." (PMID 41362702, 2025). "Collectively, higher CIP2A expression followed by RING1 reduction in lung cancer cells increases cell proliferation by c‐MYC and Cyclin B1 upregulation through inhibition of PP2A activity." (PMID 41362702, 2025). "Knockdown of RING1 increased lung cancer cell proliferation and migration in vitro and in vivo, linked to the upregulation of CIP2A and its downstream molecules, c‐MYC and Cyclin B1." (PMID 41362702, 2025). "This study revealed that NNK exposure enhances DNMT1 activity and consequently suppresses the transcription of RING1 in lung cancer cells." (PMID 41362702, 2025). "By summarizing the current understanding of the molecular mechanisms of lung cancer development and progression, we aim to propose CIP2A and RING1 as novel therapeutic targets for treating lung cancer." (PMID 41362702, 2025). "RING1 was hypothesized to potentially influence lung cancer progression through the regulation of CIP2A protein levels." (PMID 41362702, 2025). "In conclusion, this study highlights the critical roles of CIP2A, RING1, and DNMT1 in the development and progression of lung cancer." (PMID 41362702, 2025). "The development and progression of lung cancer involve the dysregulation of several molecular pathways, including those involving CIP2A, RING1, and DNMT1 proteins." (PMID 41362702, 2025). "So it is hypothesized that NNK downregulate RING1, as a TSG, in lung cancer progression due to cigarette smoking." (PMID 41362702, 2025). "Moreover, we discovered that the E3 ubiquitin ligase, RING1, plays an important role in regulating the protein stability of CIP2A in lung cancer formation." (PMID 41362702, 2025). "Data from previous experiments showed the roles of RING1 and CIP2A in lung cancer development." (PMID 41362702, 2025).
primordial dwarfism (1 paper, 2025). "Yet unlike LUSYAM, RING1-related disorder is characterized by growth restriction, primordial dwarfism and early-onset schizophrenia." (PMID 40831499, 2025).